IL33 (interleukin 33)
Diseases named in the same sentence as IL33 in open-access papers (continued):
Sharing a sentence is not in itself a finding about the gene and the disease.
asthma (continued). "RV infection of humans or mice upregulates Th2 inflammatory markers, including interleukin-13 (IL-13), interleukin-25 (IL-25), and interleukin-33 (IL-33), which may induce RV-driven exacerbation of asthma symptoms and drive remodeling." (PMID 37773065, 2023). "IL-33 itself could be a target for asthma therapy, and different studies evaluated the effects of hydrogen gas on asthma and tried to clarify the underlying molecular processes." (PMID 36675299, 2023). "In this context, IL-33 has been found to produce airway inflammation, hyperresponsiveness, and goblet cell metaplasia in allergen-naïve mice, and in allergen-exposed mice, it aggravates asthma-like responses." (PMID 37240045, 2023). "We demonstrate that IL-33 is a key inducer of type-2 cytokine production in Tc cells in vivo, providing a direct link between respiratory viral infections, Tc1-to-Tc2/Tc9 plasticity and asthma exacerbations." (PMID 37612281, 2023). "Interleukin‐33 (IL‐33) exacerbates asthma probably through type 2 innate lymphoid cells (ILC2s)." (PMID 37357549, 2023). "The targeted inhibition or knockout of IL-33/ST2 can prevent asthma." (PMID 36834541, 2023). "This is a critical gap to fill in allergy and asthma studies as many studies don’t verify protein expression of hormone receptors, nor do they examine changes in receptor expression during various activating stimulation (i.e., following IL-33 activation)." (PMID 36609358, 2023). "Finally, HDM stimulation combined with RV and SARS-CoV-2 infection resulted in higher secretion of IL-33 in the epithelium of patients with asthma when compared to healthy controls." (PMID 37087523, 2023). "IL-33 and its receptor subunit ST2 (suppression of tumorigenicity 2, encoded by IL1RL1) levels are elevated in asthmatic patients and mice and linked to the severity and steroid resistance of asthma." (PMID 37607012, 2023). "Compared with the healthy control population and mild to moderate asthma patients, immunohistochemical staining and qPCR detection results showed that airway epithelial cells in severe asthma patients expressed higher levels of IL-33." (PMID 38082335, 2023). "For instance, it was recently shown that cGAMP triggered HDM extract-induced asthma in mice via IL-33 in a TBK-1 dependent manner which could be antagonized by the bona fide TBK-1 inhibitor amlexanox." (PMID 37090735, 2023). "In summary, many factors are involved in the variable response of asthma patients to SARS-CoV-2 infection, including the asthma phenotype, the corticosteroid treatment regimen and the role of cytokines such as IL-33 and IL-13 in potentiating the T2-high response." (PMID 37679779, 2023). "An important role for IL-33 is activating type 2 innate lymphoid cells (ILC2s), which produce IL-5 and IL-13 to activate T-helper-2 cells and promote the persistence of airway eosinophilia in patients with severe asthma." (PMID 37545493, 2023). "We aim to conduct this meta‐analysis and evaluate the feasibility of IL‐33 in peripheral blood that may act as a promising biomarker in asthma." (PMID 37102668, 2023). "Our data identify Tc cells as major producers of type-2 cytokines in severe asthma and during exacerbations that are remarkably sensitive to alterations in their inflammatory tissue micro-environment, with IL-33 emerging as an important regulator of Tc2 formation." (PMID 37612281, 2023). "More interestingly, the results from 2 recent phase II clinical trials show that monoclonal antibodies targeting IL-33 (itepekimab) or ST2 (astegolimab) are beneficial to patients with asthma by reducing blood eosinophils, improving lung function, or lowering exacerbation rate." (PMID 37607012, 2023). "Whether it is children or adults with asthma, if the concentration of IL-33 increases, the symptoms will be more severe." (PMID 38082335, 2023). "In addition, IL‐33 and IL1RL1 (ST2) variants are reported to be significantly associated with asthma." (PMID 37357549, 2023).
asthma (continued). "Allergen exposure or viral infection can stimulate the secretion of IL-33 and lead to asthma." (PMID 38082335, 2023). "Asthma model mice and ICAM-1 deficient mice challenged intranasally with IL-33." (PMID 37947634, 2023). "This suggests incorporating T2‐low asthma in anti‐IL‐33 trials." (PMID 35986608, 2023). "IL-6 can also induce neutrophils to release soluble IL-6R which can act locally within the airway to activate eosinophils and act on airway epithelial cells to impair epithelial tight junction integrity and induce matrix metalloproteinases and the alarmin IL-33, contributing to pathology in asthma." (PMID 37180449, 2023). "Furthermore, polymorphisms in IL33 and IL1RL1 have been associated with an increased risk of asthma in several genome-wide association studies involving a diverse range of geographical populations." (PMID 37607012, 2023). "IL-33, a member of the IL-1 cytokine family, is constitutively expressed by both epithelial and endothelial cells, and genetic variations of IL33 and its receptor IL-1RL1 (ST2) have been associated with asthma in humans." (PMID 37759430, 2023). "IL-33, belonging to the IL-1 family, can promote bronchial remodeling and lung fibrosis by targeting various key effector cells in the adaptive immune system and innate immune system, thus further accelerating asthma development." (PMID 39282108, 2023). "IL-33 belongs to the IL-1 family, and its expression is positively related to asthma severity." (PMID 39282108, 2023). "Interestingly, 2 recent phase II clinical trials have indicated that mAbs blocking either IL-33 or its receptor ST2 were beneficial for certain subsets of patients with asthma." (PMID 37607012, 2023). "Additional studies show that RV infection may exacerbate preexisting Th2 inflammation in asthma patients, particularly through the upregulation of Th2 cytokines including IL-33." (PMID 37773065, 2023). "For example, interleukin-33 (IL-33) is a protein that has been shown to promote allergic inflammation in asthma and may be a potential target for biologicals." (PMID 37631365, 2023). "Analysis of the most versus least enriched (upper versus lower tertiles) U‐BIOPRED asthma patients for each of the IL‐33 signatures in sputum does not reveal any association with age, body mass index (BMI) or sex." (PMID 35986608, 2023). "TSLP and IL-33 are also potentially involved in the pathogenesis of asthma." (PMID 37569890, 2023). "The enrichment of IL‐33 pathway activation in T2‐low asthma may be influenced by oral corticosteroid (OCS) use in severe asthmatics driving neutrophilia." (PMID 35986608, 2023). "Consequently, airway epithelium in patients with T2 asthma overproduces a broad pallet of pro-inflammatory cytokines and mediators including alarmins (IL-25, IL-33, TSLP), as well as IL-6, IL-8, IL-1α/β, RANTES, or TNF in response to environmental triggers." (PMID 37199256, 2023). "IL-33 is a potent inducer of type-2 immunity that is elevated in the lungs of asthma patients." (PMID 37612281, 2023). "However, in patients with associated asthma (n = 13, 29.54%) and allergies (n = 16%) who may be subjected to false positive IL-33 overexpression, we cannot demonstrate to what extent the high values of IL-33 are associated with CRS or allergies, or, respectively, asthma." (PMID 38137606, 2023). "In severe asthma, a mixed inflammatory phenotype is also characterized by increased IL-33 levels." (PMID 37153601, 2023). "Moreover, the peripheral blood and induced sputum of patients with asthma contain higher IL-33 levels and ILC2 frequencies than those of control subjects." (PMID 37696896, 2023). "More specifically, IL-6 and IL-33, two pro-inflammatory cytokines produced by airway epithelia known to play key roles in severity of asthma inflammation, were modestly yet significantly upregulated in HDM-exposed mice following Miro1 deletion in club cells when compared to Ctrl HDM-challenged mice." (PMID 37377691, 2023).
asthma (continued). "Although our study has revealed some novel downstream effects of IL‐33 in asthma, there are some factors that may interfere with the interpretation of the results." (PMID 35986608, 2023). "IL-33 has been considered a major inducer of influenza–asthma exacerbations in animal studies." (PMID 37685567, 2023). "The significance of IL-33 in airway allergy is supported by genome-wide association studies, which have associated genetic variants of IL33 and its receptor ST2/IL1RL1 to airway allergy and Th2-driven asthma." (PMID 37810200, 2023). "The importance of IL-33 and alveolar epithelial cells in asthma is well-described." (PMID 36145419, 2022). "Furthermore, the importance of TSLP and IL-33 in the pathogenesis of asthma has been confirmed by studies showing efficacy of drugs that block these cytokines." (PMID 35406669, 2022). "IL-33 is induced in the epithelium following RSV infection in asthmatic subjects and infection of MCs with RSV causes an antiviral response suggesting they are beneficial in RSV-induced exacerbations of asthma." (PMID 36366528, 2022). "IL-33 is a central component for activation of both the innate and adaptive arms of immunity, and in this capacity release of IL-33 into the airways plays an important role in the pathobiology of asthma." (PMID 35406669, 2022). "However, IL-33-stimulated mast cells are also important for balancing immune homeostasis in models of asthma, promoting the expansion of Treg cells, and protecting against the development of airway hyperresponsiveness." (PMID 34531552, 2022). "Clinical trials of anti-IL-33 therapies for asthma are already underway." (PMID 35720347, 2022). "IL-1receptor-like 1 (ST2) promotes asthma development by mediating the response to IL-33." (PMID 36078171, 2022). "Variants included in our analysis of IL33 both increased and decreased risk for asthma development, however, we do not yet know if the minor alleles increase or decrease expression of IL33 in relevant tissues following viral exposure." (PMID 36685501, 2022). "In patients affected by severe asthma refractory to steroids, IL-33 activates type 2 innate lymphoid cells (ILC2s), which may promote persistent airway eosinophilia." (PMID 36140430, 2022). "Moreover, experimental studies suggest that IL-33-induced activation of MCs participates in key features of asthma." (PMID 35493481, 2022). "However, in contrast, enhanced synthesis of pro-inflammatory cytokines in asthma, such as IL-4, IL-5, IL-13, and IL-33, can contribute towards maintaining the lean state." (PMID 35807067, 2022). "Additionally, randomized controlled trials have recently shown the efficacy of biologics for targeting epithelial-derived cytokines, such as TSLP and IL-33, in patients with severe asthma." (PMID 35911708, 2022). "TSLP, IL-33 and IL-25 are epithelial cell-derived cytokines that stimulate group 2 innate lymphoid cells (ILC2s) to release type 2 cytokines such as IL-5 and IL-13 and play an important role in asthma pathogenesis." (PMID 35292112, 2022). "In asthma mouse models, the IL-33/ST2 activation in mast cells triggered a Th17 immune response." (PMID 35328556, 2022). "In terms of an innate immunological barrier, epithelial cell activation and the release of epithelial cell cytokines, such as the alarmins, IL-25, IL-33, and thymic stromal lymphopoietin (TSLP), play a significant role in causing and exacerbating allergic diseases such as asthma." (PMID 36077310, 2022). "Our results for IL33 demonstrate that while several single variants within this gene were nominally associated with asthma, no single variant achieved the same level of statistical significance as they did in aggregate." (PMID 36685501, 2022). "In the OVA and IL-33-treated asthma mouse model, enhanced activated macrophage differentiation is induced in females compared with that in male mice, along with a mechanism dependent on IL-13 production and the signal transducer and activator of transcription 6 activation." (PMID 35625578, 2022).
asthma (continued). "In the lungs IL-33 potently stimulates airway contraction, mucus production, and goblet cell hyperplasia through early induction of IL-13 in ILC2s, and plays important roles in allergic diseases and asthma." (PMID 36263033, 2022). "TSLP and IL33 may be important new targets individualized for asthma treatment, and antibody-based drugs for these pathways are being developed." (PMID 36685501, 2022). "The clinical course of asthma with fungal sensitization is similar to the clinical picture of asthma without sensitization to fungi except for the lower age of symptom onset and significantly higher levels of IgE and IL-33 in the serum." (PMID 36294955, 2022). "Also, it is conceivable that M2 macrophages contribute to the asthma phenotype not only by stimulating epithelial cell IL-33 expression, but also by producing IL-13." (PMID 36032072, 2022). "And the expression level of IL-33 in the serum of asthma patients was also reduced." (PMID 35578178, 2022). "Previous studies have also confirmed elevated IL-33 serum level in asthma patients." (PMID 35752781, 2022). "In T2-low asthma, respiratory viruses, bacteria, fungi and cigarette smoke can induce the release of epithelium-derived alarmin [i.e., IL-33, thymic stromal lymphopoietin (TSLP) and IL-25], which activate a variety of cells of the innate and adaptive immune system." (PMID 34342773, 2022). "Anti-IL-33 antibody treatment was shown to prevent the negative histological adaptations commonly associated with asthma in an OVA-induced asthma mouse model." (PMID 35159396, 2022). "Additionally, IL-33 promoted the ILC production of IL-13 in asthma patients, whereas it promoted the natural killer cell production of IFN-γ in control subjects." (PMID 36077310, 2022). "Combined with our results, it can be inferred that AS1517499 could improve the symptoms of AD by regulating IL-33 expression, thus having an important effect on asthma." (PMID 35177102, 2022). "Thus, IL-33, a member of the IL-1 family, is an important inflammatory driver in eosinophilic inflammation and asthma." (PMID 35720347, 2022). "Increased expression of IL-33 has been observed in murine asthma and in human asthma and rhinitis." (PMID 35807067, 2022). "For example, asthma associates with damaged epithelial cells and activated myeloid cells, which produce alarmins such as IL-15, IL-25, thymic stromal lymphopoietin (TSLP), and IL-33, have been observed to directly activate ILC2s." (PMID 36466877, 2022). "GWAS have shown that polymorphisms in the IL-33 gene are associated with asthma susceptibility, however the impacts of these polymorphisms are not restricted to the risk of asthma." (PMID 36292755, 2022). "TSLP, IL-25 and IL-33, are designated as alarmin cytokines because their release from microbial, pollutant or allergen-perturbed epithelia heralds the onset of inflammatory responses in asthma." (PMID 36311787, 2022). "Asthma and IL-33 signaling are also related to some cases of the intestinal inflammation." (PMID 36494354, 2022). "Similarly, IL-33 has been implicated in the pathogenesis of chronic obstructive pulmonary disease (COPD), asthma, IBD, obesity, diabetes, cardiovascular and musculoskeletal diseases, and cancer." (PMID 36263033, 2022). "In this context, it is obvious to mention the successful development of the fully human antibody REGN3500, which specifically recognizes human IL-33, is able to efficiently block the IL-33 downstream signaling and is currently under clinical development for the treatment of asthma and COPD." (PMID 34177944, 2021). "Finally, the levels of miR-3934 in PBMCs were negatively correlated with the serum levels of IL-6, IL-8, and IL-33 in asthma patients, respectively." (PMID 33506046, 2021). "We hypothesized that the differentially expressed epithelial miRNAs between the 2 asthma subsets may contribute to IL-25, IL-33, and TSLP expression in asthma." (PMID 33945508, 2021). "IL-33 is highly expressed in bronchial epithelial cells of asthma." (PMID 33722239, 2021).
asthma (continued). "Indeed, IL33 and its Interleukin 1 receptor-like 1 (IL1RL1) receptor are among the most highly replicated susceptibility loci for asthma." (PMID 34930320, 2021). "A similar pattern of IL-33 deposition was observed in children with steroid-resistant asthma." (PMID 33968043, 2021). "Monoclonal antibodies against IL33 and its receptor are in late-stage development for asthma and could also be explored in COVID-19." (PMID 33704068, 2021). "Oxidative stress has been identified as an elicitor of TSLP production, although this has not been proven in the skin, and IL-33 and IL-25, have been linked to it in other allergic diseases such as asthma." (PMID 34944487, 2021). "The finalized results of the asthma-related clinical trials will shed light on whether blockade of the IL-33/ST2 axis can affect eosinophilopoiesis and translate into clinically relevant outcomes." (PMID 33669458, 2021). "However, few studies have explored the role of IL-33 in HDM-induced asthma models under PM exposure." (PMID 34254951, 2021). "IL-33 levels are also increased in mice models of asthma, where its blockade is protective." (PMID 34960788, 2021). "Considering that IL-33 is a biomarker for early diagnosis of childhood asthma, it is intriguing to speculate about the effects of targeting IL-33 axis in the paediatric population." (PMID 34608100, 2021). "Furthermore, HpBARI, a protein secreted by the parasite H. polygyrus, is able to bind and block ST2L, inhibiting IL-33 responses in a murine model of asthma." (PMID 35011670, 2021). "Here, we investigated the role of CDG in fungal allergen and IL-33 driven asthma models." (PMID 33679760, 2021). "Particularly important in asthma pathophysiology, imiquimod treatment of HBECs from steroid-free asthmatic patients reduced (P<0.01) the gene expression of the allergic disease-related alarmin IL-33." (PMID 34950134, 2021). "Also, to directly test the regulatory impact of the 5 kb region, we selectively deleted this asthma-associated DNA segment from the full BAC and assessed the resultant IL33 expression in vivo, in mice harboring either the full length or the 5 kb deletion BAC." (PMID 34675193, 2021). "Trm cells express the IL-33 receptor ST2, suggesting they could be directly activated by epithelial-derived IL-33 and contribute to the chronicity of the asthma pathogenesis." (PMID 34868033, 2021). "BALF (IL-25, IL-33, etc.), induced sputum (eosinophils, Th2 cells, etc.), and airway remodeling could all be used as a useful indicator for asthma diagnosis." (PMID 34136532, 2021). "Of interest, a loss of function in the IL-33 gene has been shown to be protective against asthma in humans, with no harmful effects (i.e. cardiovascular abnormalities) reported." (PMID 34723980, 2021). "Consistent with a role of epithelial-derived alarmins as activators of type 2 cytokine production in the context of the disease, genome wide association studies identified the genes of IL-33 and its receptor IL1RL1 as highly replicated asthma susceptibility loci." (PMID 34177944, 2021). "Children who carried the asthma risk allele at rs1888909 or rs992969 had more IL-33 protein compared to children not carrying these alleles." (PMID 34675193, 2021). "Biologics targeting the IL-33 pathway are in clinical evaluation in adult patients with asthma." (PMID 34608100, 2021). "Interleukin-33 (IL-33), which is a member of the IL-1 family, has been shown to function in many essential physiological processes and be involved in the onset of many diseases, such as asthma, cardiovascular disease, obesity, and cancer." (PMID 33946554, 2021). "Interestingly, in severe asthma, there is increased expression of receptors for IL-33 and IL-25 on basophils, particularly after IgE stimulation." (PMID 35126131, 2021). "We have shown that neutrophils could contribute to the regulation of IL-33 processing in vivo in an Alt-induced asthma model." (PMID 34484177, 2021).